HNF1B (HNF1 homeobox B)
Diseases named in the same sentence as HNF1B in open-access papers (continued):
Sharing a sentence is not in itself a finding about the gene and the disease.
endometriosis (26 papers, 2013 to 2025). The growth of functional endometrial tissue in anatomic sites outside the uterine body. "HNF-1b (hepatocyte nuclear factor) overexpression and loss of ER/PR (estrogen receptor, progesterone receptor) expression were also present in atypical endometriosis as in CCC." (PMID 40364006, 2025). "Recent research suggest that many putative driver genes and aberrant pathways including ARID1A mutations, PIK3CA mutations, MET activation, HNF-1β activation, and miRNAs dysfunction, play crucial roles in the malignant transformation of endometriosis to OCCC." (PMID 34659566, 2021). "We have reported a variety of molecular events such as ARID1A mutations, PIK3CA mutations, MET activation, HNF-1β activation, and miRNA dysfunction in endometriosis-associated OCCC." (PMID 34659566, 2021). "The ARID1A, PI3K/AKT/mTOR, MET, and HNF-1β pathways are frequently activated and are considered promising targets for the treatment of endometriosis-associated OCCC." (PMID 34659566, 2021). "Single-nucleotide polymorphisms (rs11651755) in HNF1B were found to be associated with endometriosis and modified the risk of ovarian cancer, as well as endometriosis." (PMID 34067626, 2021). "The second way was genetic mutations in endometriosis tissues, such as hepatocyte nuclear factor-1β (HNF-1β) and ARID1A." (PMID 27854255, 2016). "With promoter hypomethylation, the expression of HNF-1β is significantly upregulated in endometriosis and endometriosis-associated ovarian CCC." (PMID 24179489, 2013). "From a biological standpoint, support for this hypothesis derives from the investigation of the hepatocyte nuclear factor (HNF-1β) overexpression in clear cell carcinoma of the ovary associated with endometriosis." (PMID 37189525, 2023). "More importantly, HNF1β appears to be integral to the transformation of endometriosis lesions, serving as the master regulator of an antioxidant detoxification system responsible for resisting the oxidative microenvironment caused by hemolysis during the development of endometriosis." (PMID 34737943, 2021). "Studies have shown that HNF-1β is an effective molecular marker for endometriosis and OCCC tumors and is overexpressed in 40% of endometriotic cysts without malignancy and in almost all cases of OCCC." (PMID 36873929, 2023). "Expression of HNF-1β was identified in endometriosis, atypical endometriosis and OCCC, implying a shared molecular pathogenesis." (PMID 34659566, 2021). "HNF-1β is critical for cell survival in endometriosis and OCCC and involves the features of OCCC, including glycogen accumulation in cancer cells, strong anti-apoptotic activity and chemo-resistance due to lower cell proliferation." (PMID 34659566, 2021). "miR-200b-3p was associated with the transcription factors DNMT1, EZH2, HNF1B, JUN, MYB, ZEB1, and ZEB2 during the pathogenesis of endometriosis." (PMID 32802844, 2020). "A transcription factor hepatocyte nuclear factor 1-beta (HNF-1β) is upregulated in endometriosis and CCC, suggesting that HNF-1β is a key molecule in endometriosis-associated clear cell carcinogenesis, and is a putative anticancer target." (PMID 29707125, 2018). "Regarding to the expression of HNF-1β in non-neoplastic tissue and neoplasms of the female genital tract, only a few studies have analyzed HNF-1β expression in endometriosis, normal endometrium, and tumors of cervix, endometrium and ovary." (PMID 25884453, 2015). "Both ARID1A and HNF1B play a role in the pathogenesis of ovarian CCC arose in endometriosis and both were proposed as new experimental markers in EC." (PMID 25885815, 2015). "Some recent studies have found expression of HNF-1β in some cases of endometriosis (particularly atypical or with inflammatory changes) and in normal endometrium, especially in the secretory phase or gestational state." (PMID 25884453, 2015).
endometriosis (continued). "The specific expression of HNF-1β and its target genes has been confirmed in not only endometriosis and CCC, but also the secretory endometrium, the Arias-Stella glands and the decidua of the placenta." (PMID 24179489, 2013). "Furthermore, hepatocyte nuclear factor-1β (HNF-1β) upregulation has been observed in both ovarian clear-cell carcinoma and endometriosis, implying a connection between endometriosis and specific ovarian cancers." (PMID 38541242, 2024). "The transcription factor hepatocyte nuclear factor 1-beta (HNF-1β) is upregulated in endometriosis and OCCC, suggesting that it might be a key molecule in endometriosis-associated CCC." (PMID 34070839, 2021). "Moreover, HNF-1β overexpression leads to detoxification to overcome persistent inflammation and oxidative stress, which are required for carcinogenesis of endometriosis." (PMID 34659566, 2021). "Furthermore, it was identified that atypical endometriosis and OCCC share molecular alterations, such as inactivating mutations for ARID1A, activating mutations for PIK3CA, and the hypomethylation of HNF1 homeobox B (HNF1B)." (PMID 29599905, 2018). "In addition, overexpression of HNF1B has been observed in atypical endometrial tissue and endometriosis and contributes to the differentiation of endometriotic epithelium to the clear cell lineage." (PMID 26910837, 2016). "However, the role of HNF-1β expression in ovarian clear cell tumors and endometriosis remains uncertain." (PMID 26675567, 2015). "HNF-1β may be a central player in the differentiation into CCC-specific lineages from endometriosis." (PMID 24179489, 2013). "Moreover, atypical endometriosis and EAOC may share several molecular alterations such as ARID1A and PIK3CA mutations, PTEN loss, MET amplifications, and HNF1B overexpression, suggesting a common molecular mechanism for malignant development." (PMID 27992377, 2017). "HNF-1β expression is characteristic of both endometriosis and OCCC, suggesting early differentiation of endometriosis into clear cell lineage." (PMID 41383608, 2025). "Based on their findings, miR-200b-3p was linked to transcription factors such as DNA methyltransferase 1 (DNMT1), enhancer of zeste homolog 2 (EZH2), Hepatocyte nuclear factor-1-beta (HNF1B), MYB, JUN, ZEB1, and ZEB2 during endometriosis pathogenesis." (PMID 36289820, 2022). "Then, DNMT1, EZH2, HNF1B, JUN, MYB, ZEB1, and ZEB2 were found as TFs related to endometriosis by interacting with target genes of miR-200b-3p." (PMID 32802844, 2020). "Recent studies have reported specific expression of HNF-1β in endometriosis and CCC and suggest that early differentiation into the clear cell lineage occurs in endometriosis." (PMID 26675567, 2015). "HNF1B overexpression has been reported to be a biomarker of ovarian clear-cell carcinoma (CCC), of its probable precursor, endometriosis and of EC." (PMID 25885815, 2015). "CCC and adjacent atypical endometriosis had HNF-1β overexpression, while benign endometriosis distant from CCC showed negative immunoreactivity for HNF-1β." (PMID 30803452, 2019). "HNF-1β is specifically upregulated in CCC, but not in EC, suggesting that HNF-1β is a key molecule in endometriosis-associated clear cell carcinogenesis and progression." (PMID 30803452, 2019). "It was subsequently extrapolated that OCCC arises from HNF-1β positive epithelial cells while OEC arises from HNF-1β negative epithelial cells of endometriosis." (PMID 29941051, 2018). "However, the role of HNF-1β in OCCC and endometriosis remains uncertain." (PMID 36873929, 2023). "A previous study demonstrated that gene expression profiling could stratify endometriosis into two molecular subtypes: transcription factor hepatocyte nuclear factor 1-beta (HNF-1β)-positive (hypomethylated) and -negative (hypermethylated) cells." (PMID 30803452, 2019).
endometriosis (continued). "Moreover, HNF-1β expression is significantly increased and ER expression is significantly down-regulated in primary OCCC lesions as compared to that in matched endometriosis, which suggests that the changes in these proteins were relatively late carcinogenic events." (PMID 29941051, 2018). "Furthermore, in a series of 12 OCCC cases with available adjacent endometriosis, nine showed positive staining for HNF-1β in the nonmalignant endometriotic epithelium, and 16 of 40 benign endometriotic cysts also showed HNF-1β positivity." (PMID 34659566, 2021).
Nephropathy (26 papers, 2018 to 2026). A nonspecific term referring to disease or damage of the kidneys. "In 2/4 patients with a genetic diagnosis of HNF1B-nephropathy, a CNV (loss) involving the whole gene was identified." (PMID 39384646, 2025). "Several genetic syndromes, such as Zellweger syndrome, VACTERL association, Eagle-Barrett syndrome, renal–hepatic–pancreatic dysplasia (RHPD), Branchio-oto-renal (BOR) syndrome, HNF1B nephropathy and renal coloboma syndrome (RCS), have been linked to kidney cystic disease." (PMID 41107504, 2025). "Consequently, the initial diagnosis of HNF1β nephropathy has sometimes been Gitelman syndrome, until genetic investigations revealed mutations in the HNF1β gene." (PMID 35894287, 2022). "Nephropathy HNF1B belongs to autosomal dominant tubulointerstitial kidney disease (ADTKD) and is characterized by enlarged kidneys, with a limited number of cysts, formed from all parts of the nephron." (PMID 41300696, 2025). "HNF1B variants, associated with autosomal dominant tubulointerstitial disease (ADTKD), lead to HNF1B-related nephropathy." (PMID 40268755, 2025). "Early-onset cystic diseases include autosomal dominant polycystic kidney disease (ADPKD), autosomal recessive PKD (ARPKD), HNF1B-nephropathy, tuberous sclerosis complex (TSC), and other ciliopathies." (PMID 39384646, 2025). "Generally, HNF1B-related nephropathy exhibits a slow progressive course in childhood, except for very early onset cases." (PMID 39337310, 2024). "Of note, primary isolated hypomagnesemia can be the first clinical manifestation of HNF1B nephropathy and genetic testing should be considered in this setting." (PMID 36672242, 2023). "While this course differentiates HNF1B nephropathy from Autosomal Dominant Polycystic Kidney Disease (ADPKD), a few cases of massive cysts mimicking ADPKD have also been reported." (PMID 36672242, 2023). "Some data are emerging on the mechanisms and progression trajectory of HNF1B nephropathy towards CKD and end-stage kidney disease (ESKD)." (PMID 36672242, 2023). "Renal structural abnormalities (RSA) are another key feature of HNF1B nephropathy and display significant heterogeneity." (PMID 36672242, 2023). "There are multiple differential diagnoses to be considered, including ADPKD, BBS, and HNF1B nephropathy." (PMID 33594464, 2021). "The newborn was clinically characterized as HNF1B-nephropathy based on a family history, objective examination and the results of laboratory and instrumental tests." (PMID 35474932, 2021). "HNF1B nephropathy: HNF1B is a transcription factor playing a central role in the tissue-specific regulation of gene expression in various organs, such as kidney, liver, biliary duct, pancreas, and genital organs." (PMID 29497606, 2018). "While for the first four study, inclusion is justified either by clinical or genetic criteria, HNF1B-nephropathy has to be confirmed genetically in order to avoid phenotypic overlap with other urinary tract malformations." (PMID 29497606, 2018). "Eligible are patients with the diagnosis of ARPKD, isolated NPH or NPH-related ciliopathies, BBS, and HNF1B-nephropathy." (PMID 29497606, 2018). "Up-to-date 344 patients have been included comprising 194 patients with NPH and related ciliopathies, 88 patients with BBS, and 62 patients with HNF1B nephropathy." (PMID 29497606, 2018). "Furthermore, there was one child with HNF1B nephropathy, one with hydronephrosis, two with cystic kidney dysplasia (one of them with LUTO), one renal agenesis, one ampullary kidney pelvis syndrome and one abdominal lymphangioma." (PMID 41107504, 2025). "In fact, bilateral defects are typical for HNF1B nephropathy." (PMID 38196016, 2024). "Hence, HNF1B nephropathy is now classified as part of the group of disorders termed Autosomal Dominant Tubulointerstitial Kidney Disease." (PMID 38674137, 2024). "HNF1B nephropathy is probably underdiagnosed among adult patients with CKD of an unknown cause, even in presence of compatible RSA." (PMID 36672242, 2023).
Nephropathy (continued). "Finally, diabetic patients with HNF1B nephropathy reaching end-stage renal disease (ESRD) are a potential candidate for simultaneous pancreatic and kidney transplantation." (PMID 36672242, 2023). "Besides, previous study reported that patients with HNF1B-related nephropathy can have hypokalemia and hypomagnesemia." (PMID 37131142, 2023). "In addition to VEO ADPKD, the broad differential diagnoses include, e.g., Bardet-Biedl syndrome (BBS), HNF1B-nephropathy, cystic kidney dysplasia, infantile nephronophthisis, and metabolic disorders including defects of fatty acid oxidation." (PMID 33594464, 2021). "We demonstrated that hyperuricemia is an early and prevalent feature in children with HNF1B nephropathy when compared to well-matched mutation negative patients." (PMID 34362049, 2021). "This, however, might be a limitation when considering hyperuricemia as a reliable predictor of HNF1B nephropathy." (PMID 34362049, 2021). "It is important to note that recent data suggest that HNF1B nephropathy shows good kidney survival." (PMID 33594464, 2021). "One important exception is the HNF1B nephropathy, which follows autosomal dominant inheritance." (PMID 29497606, 2018). "The main representatives of this group of diseases are autosomal recessive polycystic kidney disease (ARPKD), nephronophthisis and nephronophthisis-related ciliopathies (NPH/NPH-RC), Bardet–Biedl syndrome (BBS), and hepatocyte nuclear factor-1beta (HNF1B) nephropathy." (PMID 29497606, 2018). "Furthermore, renal phenotypes overlap, and although the presentation may be with proteinuria, the gene may be associated with CAKUT, kidney cysts, tubulopathy, or all 4 phenotypes, as occurs with HNF1B-nephropathy." (PMID 40303230, 2025). "Moreover, hypertension is present in 22% of children with HNF1β nephropathy." (PMID 35894287, 2022). "Interestingly, we showed that hyperparathyroidism, already described by others as a feature of HNF1B nephropathy, could also be instrumental, but probably only in those with good renal function." (PMID 34362049, 2021). "Therefore, magnesium wasting in the presence of normomagnesemia may indicate HNF1B nephropathy." (PMID 38196016, 2024). "Therefore, HNF1B defects should be considered when PTDM develops after kidney transplantation, and should also be ruled out also in the absence of any apparent risk factor, particularly in a young kidney transplant recipient with compatible features and an unknown causal nephropathy." (PMID 36672242, 2023).
ovarian clear cell cancer (25 papers, 2013 to 2025). An invasive malignant neoplasm that arises from the ovary and is characterized by a predominance of clear and hobnail malignant epithelial cells. "They found that HNF1B loss-of-function role and gain-of-function are related to serous and clear cell ovarian cancers, respectively." (PMID 30053805, 2018). "In endometrial cancer, different from ovarian clear cell carcinoma, HNF1β should be used with caution as a diagnostic marker because of its lack of specificity." (PMID 26464794, 2015). "In ovarian clear cell carcinoma, it upregulates hepatocyte nuclear factor 1β (HNF-1β) and BCL2 apoptosis regulator (Bcl-2), promoting apoptosis resistance, and sustains immune evasion and metastasis." (PMID 40361374, 2025). "HNF1B overexpression has been noted in several other tumors, including ovarian clear cell carcinoma (CCC), clear cell adenocarcinoma of the bladder, prostate cancer, and endometrial cancer." (PMID 34150416, 2021). "This idea was based on the experience from ovarian clear cell carcinoma and the presence of high hepatocyte nuclear factor-1 beta (HNF1B) levels published by Tsuchiya and colleagues, as well as the presence of upregulation in other cancers." (PMID 34150416, 2021). "In human adenocarcinomas, HNF-1B was highly expressed in ovarian clear cell carcinomas and has been recognized as a useful molecular biomarker for this entity." (PMID 30065837, 2018). "The great majority of ovarian clear cell carcinomas reported as a HNF-1β-positive and ER-negative immunoprofile." (PMID 30117003, 2018). "The transcription factor hepatocyte nuclear factor 1β (HNF1β) is ubiquitously overexpressed in ovarian clear cell carcinoma (CCC) and is a potential therapeutic target." (PMID 27346421, 2016). "HNF1β, which is highly expressed in ovarian clear cell carcinomas, was found to reduce intracellular ROS levels and enhance oxidative stress resistance." (PMID 27486766, 2016). "A probable mechanism of aberrant up-regulation of HNF1β in ovarian clear cell carcinoma is hypomethylation of the HNF1β CpG island." (PMID 26464794, 2015). "In addition, strong nuclear immunoreactivity of HNF-1B was observed in 16 of 21 (76.1%) clear cell carcinomas of the kidney, 10 of 14 (71.4%) ovarian clear cell carcinomas, 6 of 24 (25%) lung adenocarcinomas, and 4 of 15 (26.7%) prostate adenocarcinomas." (PMID 30065837, 2018). "HNF1β is also a transcription factor involved in glucose homeostasis and anti-apoptosis, and recent immunohistochemical studies have shown that it is frequently and highly expressed by ovarian clear cell carcinoma." (PMID 30117003, 2018). "The transcription factor, hepatocyte nuclear factor (HNF)-1β, may be one of several key genes involved in the identity of ovarian clear cell carcinoma (CCC)." (PMID 24179489, 2013). "HNF1B, a CCOC biomarker and a key regulator of CCOC tumorigenesis, was also on the leading edge of the clear cell ovarian cancer analysis." (PMID 35777959, 2022). "Transcription factor hepatocyte nuclear factor 1-beta (HNF-1β) enhances checkpoint kinase 1 (Chk1) activation and promotes G2/M cell cycle progression in ovarian clear cell carcinoma (CCC) following exposure to diverse genotoxic agents including bleomycin." (PMID 29707125, 2018).
ovarian clear cell cancer (continued). "Among the non-pancreaticobiliary cancers, HNF-1B was expressed in ~ 77% clear cell carcinomas of the kidney and ovarian clear cell carcinomas." (PMID 30065837, 2018). "Hepatocyte nuclear factor-1β (HNF-1β) is a transcription factor that has been shown to be significantly up-regulated in ovarian clear cell carcinoma and rarely expressed in non-clear cell carcinoma specimens." (PMID 23466883, 2013). "That is, endometrial tumors present with unmethylated HNF1B promoter status irrespective of CIMP phenotype, resembling the presentation observed for the clear cell ovarian cancer subtype." (PMID 25378557, 2015).